CEBPE (CCAAT enhancer binding protein epsilon)
Description:
Transcriptional activator. C/EBP are DNA-binding proteins that recognize two different motifs: the CCAAT homology common to many promoters and the enhanced core homology common to many enhancers. Required for the promyelocyte-myelocyte transition in myeloid differentiation.
Synonyms: C/EBP epsilon; CRP1; C/EBP-epsilon; IMD108; SGD1
Tractability: Small molecule: a structure with a bound ligand is known. Antibody: its Gene Ontology location is reachable by antibodies, with high confidence. PROTAC: UniProt records ubiquitination sites on it.
Gene: Protein-coding gene on chromosome 14 (23,117,036 to 23,120,256, reverse strand). Ensembl gene ENSG00000092067.
Subcellular location: Nucleus
Subcellular location (Human Protein Atlas): Nucleoplasm; Cytosol; Plasma membrane
Pathways (Reactome):
Developmental Biology: Transcriptional regulation of granulopoiesis
Gene Ontology:
Molecular function: DNA-binding transcription activator activity, RNA polymerase II-specific; protein binding; RNA polymerase II cis-regulatory region sequence-specific DNA binding; sequence-specific double-stranded DNA binding; DNA-binding transcription factor activity, RNA polymerase II-specific; DNA binding; DNA-binding transcription factor activity; identical protein binding; protein-containing complex binding
Biological process: granulocyte differentiation; positive regulation of transcription by RNA polymerase II; defense response; integrated stress response signaling; myeloid cell differentiation; regulation of transcription by RNA polymerase II; cellular response to lipopolysaccharide; DNA-templated transcription; regulation of DNA-templated transcription
Cellular component: nucleoplasm; nucleus; RNA polymerase II transcription regulator complex; chromatin
Genetic constraint (gnomAD): Loss-of-function variants: 10 observed, 20 expected, observed/expected ratio (o/e) 0.5, 90% interval 0.31 to 0.85. The upper end of that interval is the gene's LOEUF score, 0.85, which puts it in group 3 of 6, group 1 being the genes least tolerant of losing a copy. Missense variants: 389 observed, 390.75 expected, observed/expected ratio (o/e) 1, 90% interval 0.92 to 1.08. Synonymous variants: 179 observed, 168.17 expected, observed/expected ratio (o/e) 1.06, 90% interval 0.94 to 1.21.
Homologues: Orthologues: chimpanzee CEBPE (99% identical), macaque CEBPE (99% identical), pig CEBPE (97% identical), dog CEBPE (96% identical), rabbit CEBPE (96% identical), guinea pig CEBPE (95% identical), rat Cebpe (94% identical), mouse Cebpe (93% identical), tropical clawed frog cebpe (53% identical), Caenorhabditis elegans zip-4 (20% identical), zebrafish cebp1 (19% identical), Caenorhabditis elegans cebp-1 (17% identical), and 1 more. Paralogues in human: CEBPA (45% identical), CEBPD (33% identical), CEBPB (32% identical), CEBPG (17% identical).
Diseases named in the same sentence as CEBPE in open-access papers:
CEBPE is named in the same sentence as 29 diseases in open-access papers, as found by Europe PMC text mining. Sharing a sentence is not in itself a finding about the gene and the disease. The quoted sentences say what the papers report.
acute lymphoblastic leukemia (6 papers, 2014 to 2025). Leukemia with an acute onset, characterized by the presence of lymphoblasts in the bone marrow and the peripheral blood. "We performed an updated meta-analysis to clarify the relationship between the CEBPE rs2239633 polymorphism and the childhood acute lymphoblastic leukemia (CALL) susceptibility." (PMID 33397280, 2021). "Common allelic variants in IKZF1 (7p12.2), ARID5B (10q21.2), and CEBPE (14q11.2), which are directly related to hematopoietic differentiation and development, have been repeatedly and significantly associated with childhood acute lymphoblastic leukemia (ALL)." (PMID 24564228, 2014). "The SNPs (IKZF1 rs11978267, ARID5B rs10821936 and rs10994982, CEBPE rs2239633) were genotyped in 265 cases [169 acute lymphoblastic leukemia (ALL) and 96 acute myeloid leukaemia (AML)] and 505 controls by Taqman allelic discrimination assay." (PMID 24564228, 2014).
specific granule deficiency (3 papers, 2020 to 2025). "In another child, a heterozygous VUS c.782G>A (p.Arg261His) in the CEBPE gene, associated with specific granule deficiency, was identified." (PMID 41459527, 2025).
acute leukemia (2 papers, 2015 to 2023). A clonal (malignant) hematopoietic disorder with an acute onset, affecting the bone marrow and the peripheral blood. "For instance, we found that IKZF1 and CEBPe variants were associated with a low risk of early-age acute leukemia compared with previous international studies." (PMID 37416530, 2023).
asthma (2 papers, 2025 to 2026). "To determine the role of these key genes in the occurrence of asthma caused by environmental pollution, we provided strong evidence that the expression of genes of interest (CEBPE, HDC, IRAK3, PRR4, and SOD2) increased significantly in 160 participants with asthma." (PMID 41602038, 2026). "By conducting bioinformatics analysis, we identified five genes (CEBPE, HDC, IRAK3, PRR4, and SOD2) associated with asthma." (PMID 41602038, 2026). "After adjusting for confounding factors such as gender and age, these five genes (CEBPE, HDC, IRAK3, PRR4, and SOD2) were still independent risk factors for asthma." (PMID 41602038, 2026). "The results revealed that five genes of interest (CEBPE, HDC, IRAK3, PRR4, and SOD2) showed a strong mediating effect between PM2.5 and the onset of asthma, suggesting that PM2.5 may alter the expression of these genes, thereby causing the onset of asthma." (PMID 41602038, 2026). "Finally, five genes (CEBPE, HDC, IRAK3, PRR4, and SOD2) were identified as overlapping features across all three algorithms, as illustrated in the Venn diagram, and were thus considered robust candidate biomarkers for asthma." (PMID 41602038, 2026).
myeloproliferative disorder (1 paper, 2016). A clonal hematopoietic stem cell disorder, characterized by proliferation in the bone marrow of one or more of the myeloid (i.e., granulocytic, erythroid, megakaryocytic, and mast cell) lineages. "This analysis focused on genes (Srpk2, Hes1, Mtor, Pdp1, Meis1, Gfi1, Foxo3, Stra13, Hif1α, and Cebpε) involved in HSC proliferation; maintenance of quiescence, growth, and stem cell exhaustion; and development of myeloproliferative disorder in young and geriatric mice." (PMID 27366154, 2016).
cancer (7 papers, 2017 to 2024). A tumor composed of atypical neoplastic, often pleomorphic cells that invade other tissues. "For example, ESRRG and CEBPE interact with 15 and 5 cancer gene promoters, respectively, but interactions with our set of promoters were not reported in the literature nor in ChIP-seq experiments." (PMID 39013578, 2024). "In NB4 cancer cells, the combination treatment led to a stronger down-regulation of SPI1 in the cytoplasmic and nuclear fractions and a more pronounced down-regulation of CEBPE in the cytoplasmic fraction." (PMID 35178376, 2022).
tumor (7 papers, 2015 to 2025). "Taken together, these findings indicate that CEBPE acts as a tumor suppressor and inhibits the proliferation and invasion of MM cells." (PMID 40347515, 2025). "In particular, these genes are associated with more aggressive tumor phenotype (SAL2), migration and invasion (TOX4, PRMT5, AJUBA) development and progression (ZNF219, CEBPE)." (PMID 34944989, 2021). "Furthermore, CEBPE and SIRPG mRNA expression correlates with an anti-tumor microenvironment transcriptional profile and is linked to a “hot” immune infiltration profile in HNSC patients." (PMID 41048343, 2025). "IHC analysis of tumor tissues revealed that the protein levels of ZMYND8 and CEBPE in the ZMYND8‐KD group were significantly lower than those in the control group and that the Ki67 levels increased after ZMYND8 knockdown." (PMID 40347515, 2025). "CEBPE and SIRPG mRNA expression levels were higher in tumor than in non-tumor samples." (PMID 41048343, 2025). "For the HeH-associated SNPs in CEBPE, ARID5B, and PIP4K2A, we did not see significant preferential gain of risk alleles in tumor samples from heterozygous patients." (PMID 26575185, 2015).
infection (6 papers, 2015 to 2024). The state of being infected such as from the introduction of a foreign agent such as serum, vaccine, antigenic substance or organism. "CEBPE, a transcription factor important in neutrophil development, was differentially expressed in bone marrow neutrophils in response to infection." (PMID 38472281, 2024).
bacterial infections (3 papers, 2016 to 2025). "Human and mice lacking active CEBPE protein always suffer from frequent bacterial infections due to functionally defective neutrophils and macrophages." (PMID 28083515, 2016).
CEBPE also shares sentences with these, for which no sentence is quoted: leukemia (4 papers); acute myeloid leukemia (2); neutropenia (2); acute promyelocytic leukemia (1); atherosclerosis (1); colorectal cancer (1); COVID-19 (1); esophageal cancer (1); immune disorders (1); inflammatory bowel disease (1); influenza (1); liver cancer (1); melanoma (1); myelodysplastic syndrome (1); myeloid leukemia (1); Obesity (1); Opportunistic infection (1); Salmonella Infections (1); skin infection (1); tuberculosis (1).